HIF1A (hypoxia inducible factor 1 subunit alpha)
Diseases named in the same sentence as HIF1A in open-access papers (continued):
Sharing a sentence is not in itself a finding about the gene and the disease.
cancer (continued). "Previous literature indicates that HIF-1α expression in oxygen-depleted environments confers chemoresistance in cancers." (PMID 41305000, 2025). "In an elegant study using two model organisms for cancer cachexia, it was shown that ImpL2 in Drosophila, a direct homolog to IGFBP-5 in mammals, is under the regulation of HIF-1α and directly promotes muscle loss." (PMID 41226289, 2025). "During progression, lactate from cancer cells reinforces their glycolytic phenotype via HIF-1α/mTOR." (PMID 40422244, 2025). "HIF-1α serves as a pivotal regulator in the spectrum of cancer-related processes, encompassing metabolic reprogramming, angiogenesis, metastasis, and resistance to apoptosis." (PMID 40305214, 2025). "PTTG1 promotes angiogenesis by activating HIF-1α signaling, maintaining cancer stem cell (CSC) survival, and regulating vascular niche formation and metastasis." (PMID 41312363, 2025). "It regulates HIF-1α signaling and mitochondrial function, thereby effectively inhibiting cancer progression." (PMID 40136686, 2025). "SIRT1 also influences the Warburg effect by inhibiting HIF-1α, which is necessary for the metabolic shift to glycolysis in cancer cells." (PMID 41436543, 2025). "KRIBB11 inhibits HIF-1α’s capacity to initiate gene transcription, thereby diminishing cancer cell invasion and resistance to therapy." (PMID 40136686, 2025). "Upon low-oxygen-induced stabilization, HIF-1α translocates to the nucleus, where it upregulates genes involved in cellular metabolism, angiogenesis, and invasion, providing cancer cells with mechanisms to cope with a reduced oxygen supply." (PMID 40754534, 2025). "The interplay between HIF-1α, NF-ĸB, and HMGB1 sustains DNA damage and the accumulation of mutations, driving cancer progression and worsening prognosis." (PMID 40244228, 2025). "By examining the DepMAP data, we found that nearly all human cancer cells cultured under 2D normoxia cannot tolerate the loss of VHL, while cells tended to gain growth benefit by HIF1A knockout under normoxic oxygen conditions." (PMID 38853928, 2025). "A phase-ı clinical study of the LNA antisense oligonucleotide EZN-2968, which targets HIF-1α in advanced solid tumors, revealed the potential of this strategy in cancer therapy." (PMID 40711670, 2025). "Comprehending the clinical implications of HIF-1α establishes a basis for targeted therapeutic strategies that can enhance cancer prognosis while defending fertility." (PMID 40136686, 2025). "We analyzed data from TCGA and identified a positive correlation between MED15 and HIF1α mRNA levels across various cancers." (PMID 39947475, 2025). "The stabilization of HIF-1α under normoxia is coincidentally coherent to the aerobic features of the Warburg effect, which also features in the metabolic transformation in cancer cells." (PMID 39757165, 2025). "In BCa, our data suggest GPT2 primarily drives EMT and stemness via glutamine-derived α-KG accumulation, which differentially modulates HIF-1α/Wnt pathways compared to other cancers." (PMID 41323791, 2025). "Hypoxic stress was significant in the cancer core region as indicated by elevated HIF1α expression compared to that in the junction and normal regions." (PMID 40593569, 2025). "HIF-1α, induced under hypoxic conditions, is known to promote autophagy and chemotherapy resistance across diverse cancer types." (PMID 41353169, 2025). "The activation of HIF-1α also promotes angiogenesis to promote cancer cell survival, proliferation, and metastasis." (PMID 40863244, 2025). "This association has been confirmed experimentally with the use of rapamycin, an inhibitor of mTOR, effectively inhibiting HIF-1α accumulation and its subsequent transcriptional activity in hypoxic PC-3 cancer cells." (PMID 39965249, 2025). "The action of liposomes in modulating HIF-mediated autophagy entails a decrease in HIF-1α levels, subsequently initiating autophagic flux and resulting in the death of cancer cells." (PMID 40004215, 2025).
cancer (continued). "Dendrimers demonstrate the capacity to lower HIF-1α levels and stimulate autophagy in cancer cells, thereby facilitating autophagic cell death." (PMID 40004215, 2025). "Dauricine potentiates antitumor effects of sorafenib in human NSCLC by modulating HIF-1α-mediated pathways that are involved in several cancer hallmarks." (PMID 40205002, 2025). "In contrast, proliferating cancer cells sustain elevated glucose uptake and glycolytic activity through the combined action of HIF-1α and PI3K-Akt-mTOR signaling pathways." (PMID 41158916, 2025). "Another study demonstrated that miR-28-5p can promote cancer progression by regulating the level of HIF-1α." (PMID 41226405, 2025). "Ultimately, the experimental results showed that B7-H3 can regulate cancer cell glycometabolism by mediating HIF-1α stability through ROS." (PMID 40519928, 2025). "Given its central role in regulating multiple metabolic pathways such as amino acid metabolism, lipid metabolism, gluconeogenesis, and the tricarboxylic acid cycle, HIF-1α is a key factor in maintaining cancer cell survival and resistance to therapy." (PMID 39897552, 2025). "MSNs promote autophagy through the downregulation of HIF-1α expression, thereby facilitating cancer cell apoptosis." (PMID 40004215, 2025). "To further characterize the phenotypic changes in cells after irradiation, we analyzed the gene expression of growth factor VEGF, HIF-1α, and cytokines involved in the inflammatory response in our two cancer cell lines." (PMID 41007670, 2025). "HIF-1α emerges as a central orchestrator of these adaptations, exerting a profound impact on cancer cell metabolism." (PMID 40322886, 2025). "Hypoxia can contribute to HIF-1α, which is crucial to helping predict and survive cancer by mediating angiogenesis, glycolysis, and cancer cell invasion and migration." (PMID 41585262, 2025). "Glycolysis in cancer cells is modulated by important transcription factors and pathways, such as the HIF‐1α, AMP‐activated protein kinase (AMPK) and c‐MYC pathway." (PMID 39993964, 2025). "NF-κB also promotes cancer cell survival under hypoxic conditions by stimulating hypoxia-inducible factor 1α (HIF-1α) and inducing anti-apoptotic genes such as Bcl-2, Bcl-xL, and inhibitors of apoptosis (IAP)." (PMID 40420174, 2025). "Examining the complex relationship between HIF-1α, cancer progression, and reproductive health is essential for formulating targeted therapeutic strategies that enhance cancer prognosis while safeguarding fertility." (PMID 40136686, 2025). "Here, we outline the links between cancer and autoimmunity regarding hypoxia-induced factors, such as HIF-1α, and describe the role of hypoxia in the modulation of the autoimmune response." (PMID 40963621, 2025). "The expression of microRNA-21 increases the levels of HIF-1α through the promotion of autophagy in various cancer cell types." (PMID 40004215, 2025). "In terms of mechanism innovation, the conventional understanding is that hypoxia promotes immune evasion primarily by upregulating PD-L1 transcription in cancer cells via HIF1α." (PMID 40605065, 2025). "Cancer cells with elevated HIF‐1α levels tend to exhibit higher malignancy and poorer response to radiotherapy, leading to a worse prognosis." (PMID 40567251, 2025). "Subsequently, they applied HIF-1α inhibitors to the cancer cells and observed enhanced treatment effects using the platform." (PMID 39926198, 2025). "The upregulation of Pgp driven by HIF1-α has been observed in several cancers, including liver, laryngeal, lung and breast cancers, along with malignant pleural mesothelioma and chronic lymphocytic leukemia in B-cells." (PMID 39940704, 2025). "This phenomenon facilitates PKM2‐enhanced HIF‐1α/β‐catenin transcriptional activity and triggers a cascade reaction in aerobic glycolysis and cancer progression." (PMID 40470773, 2025).
cancer (continued). "Cancer cells create a hypoxic tumor microenvironment for their own survival where hypoxia-inducible factor 1α (HIF-1α) plays a pivotal regulatory role in metabolic reprogramming observed in hypoxic cancer cells." (PMID 40066330, 2025). "The ERCC6L/HIF-1α axis plays a crucial functional role in enhancing cancer stemness and LUAD progression both in vitro and in vivo." (PMID 40691138, 2025). "HIF-1α signaling is a known regulator of changes in cellular metabolism, for example, promoting aerobic glycolysis in a range of cancers, but also during normal development, when rapid tissue growth is required." (PMID 40802851, 2025). "When cancer cells are subjected to hypoxia, HIF‐1α accumulates in the nucleus and binds to related target genes." (PMID 41427004, 2025). "Through its regulatory role, HIF-1α facilitates the adaptation of cancer cells to environments characterized by low oxygen and nutrient availability." (PMID 41311849, 2025). "Reports on the HIF-1α/MMPs or HIF-1α/ADAMs signaling pathway in digestive system malignant tumors are still relatively rare." (PMID 40563539, 2025). "While previous studies have established that HIF-1α enhances P-gp expression in cancer cells, our results reinforce these findings by demonstrating that ERRα is essential for this process." (PMID 40723264, 2025). "The major enriched pathways included Arachidonic acid metabolism, Steroid hormone biosynthesis, Pathway in cancer, etc, and the major functional genes included the alox15b, gng7, hif1a, ppara, and pla2g." (PMID 41462646, 2025). "HIF-1α further interacts with the Notch and Wnt pathways to regulate cancer cell stemness and differentiation." (PMID 39981236, 2025). "In 2023, an interesting review on the interactions between ncRNAs and HIF-1α in cancer was published in the European Journal of Pharmacology." (PMID 40305214, 2025). "Continued research and innovation in these areas hold the potential to transform the landscape of cancer treatment by leveraging the full therapeutic potential of HIF-1α targeting interventions." (PMID 39981236, 2025). "In mammals, three oxygen-sensitive HIF-α subunits have been identified: HIF-1α, HIF-2α, and HIF-3α, with HIF-1α being the most extensively studied and broadly implicated in cancer progression." (PMID 40647184, 2025). "Previous studies have shown that HIF-1α can enhance the expression of PD-L1, facilitating cancer cell survival under hypoxic conditions." (PMID 40038276, 2025). "HIF-1α serves as a key regulator of hypoxia-induced autophagy, promoting survival of cancer cells in the presence of cytotoxic compounds and leading to the development of resistant clones." (PMID 40710312, 2025). "The cancer cell metastasis is mediated by hypoxia-inducible factor 1α (HIF1α)/zinc finger E-box binding homeobox 1 (ZEB1) axis, which is involved in the process of epithelial–mesenchymal transition (EMT)." (PMID 40863244, 2025). "For example, hypoxic conditions such as inflammation and cancer induce the release of HIF‐1α, which can contribute to metabolic reprogramming of neutrophils toward glycolysis and other anaerobic processes." (PMID 40979214, 2025). "They found that 8-nitroG was mainly concentrated in the nuclei of cancer cells, while HIF-1α was present in both the cytoplasm and nuclei." (PMID 40244228, 2025). "Hypoxia induces molecular and phenotypic changes in cancer cells, primarily through hypoxia-inducible factors (HIFs), especially HIF-1α." (PMID 40429910, 2025). "Berberine, an alkaloid present in various plants, demonstrates anti-cancer properties by inhibiting HIF-1α signaling in colorectal cancer cells (HCT116)." (PMID 40004215, 2025). "Specifically, dimeric PKM2 translocates to the nucleus in cancer cells to stabilize the transcription factor hypoxia-inducible factor 1-alpha (HIF-1α)." (PMID 40057191, 2025).
cancer (continued). "The HIF-1α isoform primarily accumulates at lower oxygen levels (0–2% O2) in cancer cell lines, while the increased level of stabilized HIF-2α is maintained during moderate hypoxia levels (2–5% O2)." (PMID 40358197, 2025). "Accordingly, EF-24-mediated inhibition of NFkB and HIF1α in cancer cells appears to be contextual, and its antitumorigenic effects are not simply exerted by regulating specific genes or pathways." (PMID 40986633, 2025). "Another study in this type of cancer has shown the HIF-1α induces an elevation in the levels of miR-361-3p within hypoxic extracellular vesicles (EVs) in the context of CRC." (PMID 40305214, 2025). "Elevated levels of HIF-1α are strongly correlated with angiogenesis, cancer resistance, metastasis, and poor prognosis." (PMID 40535814, 2025). "In summary, the hypoxia inducible factor HIF1α is undoubtedly a key regulator of metabolic reprogramming in cancer cells, enabling their sustained and uninhibited growth, particularly under hypoxic conditions." (PMID 41007296, 2025). "IER3 (immediate early response 3) and HIF1A (hypoxia-inducible factor 1-alpha) transcriptionally regulate glycolytic genes s promoting a Warburg-like glycolytic shift in cancer cells." (PMID 41171083, 2025). "Functionally, miR-22 modulated the HIF1A pathway, enhanced survival in stressful conditions, promoted a glycolytic shift, and enhanced cancer cell plasticity and sorafenib resistance via GLUT1 targeting." (PMID 40332478, 2025). "Quantitative analysis demonstrated high HIF-1α expression in 73.33% (22/30) of cancer tissues compared to 23.33% (7/30) of adjacent normal tissues (P < 0.001)." (PMID 40406267, 2025). "Under cancer conditions, hypoxic levels in the cellular microenvironment inhibited the normal physiological processes, leading to stable accumulation of HIF-1α and HIF-2α." (PMID 40963621, 2025). "Investigations have demonstrated that the application of zinc chloride to hypoxic cancer cells results in a significant downregulation of HIF-1α protein levels and its downstream target gene, VEGF, both in vivo and in vitro." (PMID 39995420, 2025). "By mediating hypoxia-adaptive pathways, HIF1-α enables cancer cells to successfully survive in low-oxygen conditions, making it a major target for cancer therapeutics development." (PMID 40507913, 2025). "Parkin was also found to prevent cancer invasion by marking hypoxia-inducible factor 1-alpha (HIF-1α) for degradation." (PMID 40361329, 2025). "In the complex interplay between environmental factors and cellular signaling pathways, emerging research suggests a significant role for obesity as a pivotal contributor to cancer progression, elucidating its capacity to drive the activation of HIF‐1α." (PMID 39969135, 2025). "The mechanism by which PDK activity is upregulated in cancer cells comes as a result of downstream activation by HIF1a, which is induced by the hypoxic TME." (PMID 41450919, 2025). "Numerous HIF-1α inhibitors have been investigated for their anti-cancer effects, with many demonstrating potential advantages in maintaining ovarian function." (PMID 40136686, 2025). "This dual mechanism potentiates PKM2‐induced transcriptional activity of HIF‐1α/β‐catenin, ultimately triggering a cascade in aerobic glycolytic and cancer progression." (PMID 40470773, 2025). "It has shown therapeutic potential across various cancers, reducing HIF-1α levels and VEGF expression in human tongue squamous cell carcinoma cells." (PMID 39470609, 2025). "Colocalization between the TUNEL signal and Hif-1α expression confirmed drug delivery deep into hypoxic cancer cells." (PMID 39744223, 2025). "The findings indicate that HIF-1α stimulates autophagy in cancer cells as a means of survival to cope with hypoxic stress circumstances." (PMID 40004215, 2025).
cancer (continued). "Through an understanding of the molecular pathways involving HIF-1α, novel therapeutic approaches targeting highly expressed HIF-1α signaling pathways have been devised to enhance personalized and precise treatment for cancer patients." (PMID 40444079, 2025). "Several natural and synthetic compounds have demonstrated the ability to modulate HIF-1α signaling, offering promising therapeutic potential against cancer." (PMID 40284037, 2025). "We examined here the potential of 2-ANPC to interact with and inhibit HIF-1α activity in vitro and in vivo across a broad spectrum of cancer cell lines." (PMID 41514626, 2025). "TGF-β plays a paradoxical role in cancer, depending on microenvironmental conditions such as oxygen levels, and is closely related to its interaction with HIF-1α, which in turn regulates the expression of many glycolysis-related genes." (PMID 40943648, 2025). "Research has shown that stabilization of HIF-1α directly induces MMPs expression and activity in various cancer types." (PMID 39968177, 2025). "LUAD cells exhibit increased expression of circ-0000211, which promotes cancer cell migration through the miR-622/HIF-1α axis." (PMID 40004471, 2025). "These techniques enable the evaluation of the interaction of phytochemicals with cancer-related molecular targets such as HIF-1α and the human androgen receptor." (PMID 40362546, 2025). "Human cancer biopsies obtained from most primary human cancers and their respective metastases exhibit elevated levels of HIF-1α or HIF-2α, or both proteins." (PMID 39470609, 2025). "Overall, this data illustrates the high potency of 2-ANPC in targeting HIF-1α and regulating its signaling in cancer cells under hypoxic conditions." (PMID 41514626, 2025). "Broadly across cancer types, hypoxia induces ERO1α expression through the activation of HIFs, particularly HIF-1α, which transcriptionally upregulates ERO1α." (PMID 41226317, 2025). "Through the inhibition of HIF-1α, ginsenosides can play an anticancer role at multiple levels, enhance drug efficacy, and inhibit the metastatic recurrence of cancer cells." (PMID 41585262, 2025). "The AKT/mTOR/HIF-1α signaling pathway is crucial in promoting glycolysis and lactation, thus contributing to the “metabolic reprogramming” of cancer cells." (PMID 40989165, 2025). "In hypoxic conditions, cancer cells stabilize hypoxia-inducible factors, with HIF-1α playing a pivotal role in conferring metabolic plasticity and facilitating immune evasion in cancer cells." (PMID 40563638, 2025). "In some forms of cancer, this is thought to create positive feedback loops, from elevated mitochondrial metabolism, to increased ROS production maintaining disinhibition of HIF-1α, which reinforces metabolic drive." (PMID 40802851, 2025). "According to some reports, HDGF induces VEGF-dependent angiogenesis by activating HIF-1α in cancers." (PMID 40770862, 2025). "The HIF-1α protein is its subunit; in hypoxia, this becomes stable and is expressed throughout the body, and there are several clinical trials in different phases with drugs that target the HIF-1α pathway for cancer therapy." (PMID 40867888, 2025). "It is noteworthy that many known genes in cancer, e.g., HIF1A, SLC16A3, EPCAM, and SOX9, were consistent, albeit in fewer datasets and so did not meet our inclusion criteria." (PMID 39774001, 2025). "The H-AsA groups showed a more pronounced reduction in HIF-1α levels compared to the L-AsA groups, highlighting the stronger effect of higher AsA concentrations in inhibiting HIF-1α, which is crucial for hypoxia regulation and cancer cell survival." (PMID 40301490, 2025).